SMIM34 (small integral membrane protein 34)
Synonyms: SMIM34A
Tractability: Antibody: UniProt predicts a signal peptide or a membrane-spanning region.
Gene: Protein-coding gene on chromosome 21 (34,414,494 to 34,423,951, reverse strand). Ensembl gene ENSG00000243627.
Subcellular location: Membrane
Gene Ontology:
Cellular component: membrane
Homologues: Orthologues: chimpanzee SMIM34 (96% identical), macaque SMIM34 (92% identical), dog SMIM34 (74% identical), pig SMIM34 (68% identical), mouse Smim34 (57% identical).